BCL2 (BCL2 apoptosis regulator)
Diseases named in the same sentence as BCL2 in open-access papers (continued):
Sharing a sentence is not in itself a finding about the gene and the disease.
tumor (continued). "However, similar to BCL6 and BCL2, KDSR is differentially expressed between tumor and normal paired FL samples (KS-test P < 0.001)." (PMID 28765546, 2017). "Increasing miR-16 expression might be a promising strategy for tumor therapy by repressing tumor angiogenesis and inducing tumor cell death through targeting VEGF and BCL2.42, 43 miR-17 is negative regulator of angiogenesis in ECs in vitro and in vivo." (PMID 28650446, 2017). "Compared with normal saline and LNPS@Scrambled Bcl-2 treated tumor-bearing mice, the expression of Bcl-2 significantly reduced, and the expression of BAX and Caspase-3 obviously increased in tumor tissue after tumor-bearing mice were treated with LNPS@siBcl-2." (PMID 28514759, 2017). "Administration with different concentrations of TFAE significantly inhibited the expression of Bcl-2 in tumor tissues when compared with tissues belonging to negative control mice." (PMID 29348766, 2017). "In addition, gallic acid, a bioactive phenol compound present in the pulp, has been shown to induce apoptosis in tumor cells by reducing the activation of EGFR, ERK1/2, and AKT proteins and downregulating the expression of Cyclin D and Bcl-2 genes." (PMID 28885570, 2017). "This study identified HER2 and Bcl-2 as independent predictors of a pCR through a logistic regression analysis, and significant reductions in tumor size were noted in HER2-positive/Tau-negative/Bcl-2-negative tumors with a high Ki67 index." (PMID 29254147, 2017). "There was a trend towards having high grade tumor, negative hormone receptors, low bcl2 expression and high Ki67 index in cases with low nuclear BRCA1 expression." (PMID 28863181, 2017). "In comparison with poorly differentiated EPNEC, the subgroup of patients with well-differentiated tumours presented comparable frequencies of ERCC1, Bcl-2, and Lin28 IHC expression, similar RR (p = 0.94), but higher Ki-67 index (p = 0.048) and numerically longer OS (p = 0.23)." (PMID 28955403, 2017). "In conclusion, DEA induces tumor cell apoptosis through multiple pathways, including cell cycle arrest, AIF nuclear translocation, PARP-1 cleavage, activation of the Bax/Bcl-2 ratio, caspase-3 activation, and inhibition of the ERK and Akt cytoprotective pathways." (PMID 29220397, 2017). "Furthermore, its expression patterns are also correlated with tumour stage, grade, proliferation (Ki67), apoptosis (apopdetek and bcl-2), and overall survival in patients with T1G3 tumours." (PMID 29207682, 2017). "Furthermore, MK enhanced tumour cell resistance to cisplatin by inducing lncRNA ANRIL expression and increasing anti-apoptotic protein Bcl-2 expression in cancer cells." (PMID 29176691, 2017). "The lack of BCL2 upregulation in the remainder of the tumor suggests that cells beyond the ‘niche’ lack the abilities to adapt in a similar manner." (PMID 28649658, 2017). "The tumor showed positive immunostaining for Vimentin, CD31, CK7, D2–40, c-MYC, Ki67, focal positivity for PanCK, and negative immunostaining for Factor VIII, CD34, WT1, CK5/6, Calretinin, EMA, HBME-1, CEA, p63, EpCAM, Bcl-2, TTF1 and Thyroglobulin." (PMID 28810922, 2017). "Tumor cells showed strong positivity for CD34, vimentin and Bcl-2." (PMID 29075420, 2017). "Furthermore, to verify the mechanisms of tumor inhibition by Bin1 in vivo, we detected the expression alterations of MMP-2, E-cadherin and BCL-2 in tumor-bearing mice using IHC." (PMID 28152502, 2017). "All these results suggest that SOCS3 is a direct target of miR-222-3p, and exosomic miR-222-3p might enhance tumor malignancy through SOCS3 and its downstream effectors, such as the Jak2/Stat3 and Bcl-2 pathways." (PMID 28743280, 2017).
tumor (continued). "Given the range of responses, we show that CIVO, a multiplexed tumor micro-dosing technology, represents a viable functional precision medicine approach for differentiating responders from non-responders to BCL-2/MCL-1 targeted therapy." (PMID 29269870, 2017). "The possible potential mechanisms for REGIA activity included: First, REGIA expression may inhibit the tumor cell apoptosis through acceleration of STAT3 and Bcl-2 expression." (PMID 29162157, 2017). "Patients with tumor tissue Bcl-2 positive and Bcl-6 negative (Bcl-2+/Bcl-6-) have the worst outcomes." (PMID 27129176, 2016). "C12 inhibited the tumor growth through inducing apoptosis in a PON2-dependent but not Bcl-2 protein-dependent manner." (PMID 26758417, 2016). "Considering that free G3139 induced mild tumor suppression in the first two weeks of treatment without corresponding Bcl-2 downregulation, the slight antitumor effect of free G3139 was probably due to immune response caused by CpG islands in G3139." (PMID 27034925, 2016). "We first tested the transcription levels of Bcl-2, Survivin, and BAX in the tumor tissues." (PMID 27248325, 2016). "Here, we show that through shRNA knockdown studies, TGFβ2 directly mediates the survival of the adaptive EGFR-TKI drug-escaping tumor cells, and that it also directly regulates the mitochondrial BCL-2/BCL-xL expression downstream, but not BIM." (PMID 27852038, 2016). "We identified that there was upregulation of BCL-2/BCL-xL prosurvival signaling and p-STAT3 activation in HCC827 cells in adaptive escape against erlotinib, primarily localizing along the peripheral rind of the tumor xenograft as in the TKI evading cells." (PMID 27852038, 2016). "Molecular analysis of the tumor tissues showed that USP22 knockdown reduced the levels of cyclin D2, Akt phosphorylation, vimentin, and Bcl-2, whereas upregulated the expressions of E-cadherin, Bax, and cleaved (cl)-caspase-3, which confirmed in vitro findings." (PMID 27145278, 2016). "Thus, Bcl-2, via its BH4 domain, cooperates with numerous proteins regulating different cellular pathways involved in tumor progression and chemoresistance such as hypoxia and angiogenesis." (PMID 27019364, 2016). "Finally, we found that overexpression of ANG2 resulted in changes in the expression of tumor formation-related proteins including vimentin, E-cadherin, Bim, PUMA, Bcl-2, Bax, Cyclin D1, PCNA and CD31." (PMID 27492854, 2016). "In addition, the protein expression of NF-κB, BCL-2, MRP-1, P-gp, and BCRP were down-regulated, and expression of caspase-3 and Bax were up-regulated in tumor tissue by using DOX/RES-loaded NPS." (PMID 27731405, 2016). "Affymetrix mRNA profiling of the in vivo tumor samples revealed no significant changes in BCL-2, MCL-1, BCL-XL and BIM mRNA levels after ABT199 treatment." (PMID 27056887, 2016). "CXCL12/CXCR4 axis plays a crucial role in determining the homing of metastatic tumor cells with poor prognosis, which the expression of CXCR4 and Bcl-2 and PI3K/Akt and ERK1/2 signaling are controlled and the level at which it is expressed mark the difference between normal and pathological events." (PMID 27668882, 2016). "The immunohistochemistry results indicated that LNT induced tumor cell apoptosis indicated by an increase of the TUNEL-positive cell numbers (TUNEL panel) and Bax expression (Bax panel), and a decrease of Bcl-2 expression (Bcl-2 panel)." (PMID 27353254, 2016). "We also presented the first in vivo proof-of-concept evidence to support the efficacy of combination BCL-2/BCL-xL BH3 mimetic with EGFR TKI in circumventing early adaptive drug resistance and thus resulting in durable tumor response in EGFR-mutant NSCLC precision therapy." (PMID 27852038, 2016).
tumor (continued). "The tumor cells were diffusely positive for vimentin, focally positive for S-100 and bcl-2, sparsely positive for cytokeratin, and negative for EMA and c-kit." (PMID 27068820, 2016). "The expression of caspase-3 and Bcl-2 were regulated simultaneously in the tumor tissues of UL138 expression, indicating that Tet-On system-controlled UL138 expression in the xenograft animal model induced tumor cell death by apoptosis." (PMID 26735338, 2016). "Here, we present the evidence that C12 preferentially triggers transformed cell apoptosis in vitro and inhibits transplanted tumor growth in vivo as a single agent independent of both anti- and pro-apoptotic Bcl-2 proteins." (PMID 26758417, 2016). "The level of BCL-2 after treatment was detected by western blot analysis, LPH-PolyMet-siBCL2 induced a significant downregulation of BCL-2 level in comparison with all other groups and the TUNEL assay further confirmed the induction of apoptotic cells in tumours." (PMID 27264609, 2016). "Meanwhile, AQP9 knockdown downregulated bcl-2 expression and induced activation of bax and caspase-3, suggesting that AQP9 knockdown reduced proliferation and increased apoptosis which contributed to its suppressive effect on tumor growth." (PMID 27187384, 2016). "Recently, several small molecules triggering apoptosis independent of either pro- or anti-apoptotic Bcl-2 proteins have been identified as potential anti-tumor drugs." (PMID 26758417, 2016). "We observed, in DLA the levels of Bax protein expression increased significantly after MEAC treatment of the tumor host, whereas, no significant change in the level of Bcl-2 was observed." (PMID 27980586, 2016). "Using RCC cell lines, we have revealed that inhibition of GSK-3 results in decreased expression of NF-kB target genes Bcl-2 and XIAP leading to a subsequent increase in RCC apoptosis and the anti-tumor effect of sorafenib, TKI available for treatment of mRCC in clinical practice." (PMID 27387559, 2016). "Taken together, these results indicate that overexpression of anti-apoptotic Bcl-2 proteins reduces apoptosis in response to the classical anti-tumor drug actinomycin D but fails to provide protection against C12." (PMID 26758417, 2016). "Tumor inhibition response attributes to the synergistic effect of PTX potency and MDR reversing ability of Bcl-2 siRNA in the tumor supporting that kojic acid based liposomal pH-sensitive nanocarrier as efficient vehicle for systemic co-delivery of drugs and siRNA." (PMID 27786239, 2016). "This structure based-redesigned version of ABT-263 has shown suppression of tumor growth and a higher specificity for Bcl-2 without losing affinity." (PMID 26936767, 2016). "In addition, we examined the expression of apoptotic and proliferation genes including Bcl-2, cyclinD1 and cyclinB1 in HepG2 and SMMC7721 cells and tumor of xenograft mice." (PMID 26921196, 2016). "However, this trend was overpowered by the striking AID−-dependent tumor acceleration seen upon comparison of BCL2+AID− mice (216 days) and BCL2+AID+ mice (384 days, P<10−4)." (PMID 27813533, 2016). "The tumor cells showed positive immunoreactivity for synaptophysin, chromogranin A, ER, PgR, and bcl-2 and negative (or almost negative) immunoreactivity for HER-2." (PMID 28105053, 2016). "Accordingly, one strategy for cancer therapy is to identify agonists that activate apoptotic pathway independent of Bcl-2 proteins in tumor cells." (PMID 26758417, 2016).
tumor (continued). "Compared with those molecules, C12 is the first small molecule compound, to the best of our knowledge, inducing human tumor cell apoptosis in vitro as well as blocking tumor growth in vivo independent of both pro- and anti-apoptotic Bcl-2 proteins." (PMID 26758417, 2016). "Although our model supports findings of increased VEGFA expression in response to hypoxia, this loop was not sufficient to induce Bcl-2-mediated tumor cell survival in the in vivo setting." (PMID 26959744, 2016). "Our data indicate that, unlike most apoptotic inducers, C12 evokes a novel form of apoptosis in tumor cells through inducing mitochondrial membrane permeabilization independent of both pro- and anti-apoptotic Bcl-2 proteins." (PMID 26758417, 2016). "Therefore, we treated WT and Keap1-/- MEFs, as well as the panel of 20 human tumor lines, with RTA 405 and measured the protein levels and activities of NRF2, BCL2 and IKKβ." (PMID 26301506, 2015). "Together, these results show that PCAF can induce cell apoptosis by modulating a GLI1/Bcl-2/BAX axis that in turn suppresses HCC progression, and suggest that 5-FU may exert a stronger anti-tumor effect in patients with PCAF expression in HCC tumors." (PMID 25855960, 2015). "Our previous work indicated that curcumol induced tumor cells apoptosis via down-regulation of Bcl-2, while the mechanism is not very clear." (PMID 26307972, 2015). "Bcl-2 inhibitors, STAT3 inhibitors, and therapeutic strategies modulating BCR signaling, tumor microenvironment and cytokine/chemokine axes may help in the management of CD5+ DLBCL patients." (PMID 25760242, 2015). "Immunohistochemically, the tumor showed strong and diffuse staining for CD34, bcl-2, and vimentin; other markers, such as pan-cytokeratins, EMA, desmin, alpha-smooth muscle actin, and S-100 protein, were negative and had a high mitotic index (seven mitoses per 10 high-power fields (HPF))." (PMID 25649645, 2015). "Three additional genes, BCL2, PRIMA1, and PTGDR showed hypermethylation only in tumour samples." (PMID 26482433, 2015). "FL tumor cells, characterized by CD10, bcl-2 and bcl-6 immunoreactions, are arranged in follicular structures of irregular sizes that may resemble reactive follicles but with a lost polarization." (PMID 25815348, 2015). "The anti-tumor action of TW-37; which also binds to the BH3 groove of Bcl-2; is assumed to be due to a combination of a pro-apoptotic and specific anti-angiogenic effects as described in head and neck small cell carcinoma; pancreatic cancer; and lymphoma cells." (PMID 25690034, 2015). "Finally, immunohistochemical analysis revealed that SCL treatment significantly increased Bax expression and decreased Bcl-2 and vascular endothelial growth factor (VEGF) expression of H22 tumor tissues in a dose-dependent manner." (PMID 26426041, 2015). "Given the relationship between KEAP1, IKKβ, BCL2, and cancer, we investigated whether the tumor cell lines with high basal NRF2 activity also had elevated IKKβ and BCL2 protein levels." (PMID 26301506, 2015). "The possible factors that may contribute in potential tumor invasion and metastasis are MMP-9, Bcl-2 and Cyclin D1 genes which are known to be regulated by AP-1." (PMID 26581505, 2015). "In addition, we also observed decreased expression of survivin, bcl-2, EGFR and induced PARP cleavage in tumor lysates from nude mice bearing ACHN cells as a xenograft and treated with DIM-C-pPhOH (30 mg/kg/d)." (PMID 26035713, 2015). "Immunohistochemical staining of tumor tissue revealed that TQ treatment at the doses of 5mg/kg and 20mg/kg increased the expression of p21 protein, while this treatment inhibited the expression of NICD1 and Bcl-2 vs. controls." (PMID 26416455, 2015). "Taken together, our results demonstrated that miR-206 suppressed c-Met and Bcl2 expression in NSCLS and could function as a potent tumor suppressor in c-Met/Bcl2-over expressing tumors." (PMID 26325180, 2015).
tumor (continued). "Similarly, human tumor cell lines with high basal NRF2 activity also tend to have elevated IKKβ and BCL2." (PMID 26301506, 2015). "Although several binding partners have been shown for G0S2 including Bcl2, ATGL and Nucleolin, our studies suggest that inhibition of ATGL can attenuate cell growth in a wide range of tumour cells and is an important mechanism of G0S2-mediated growth inhibition." (PMID 26318046, 2015). "Thus, mitochondrial NR4A1 exhibits tumor suppressor-like activity, and both paclitaxel and peptide mimetics of NR4A1 that bind bcl-2 also activate apoptosis in cancer cells." (PMID 26035713, 2015). "Therefore, there is substantial interest in developing chemotherapeutic drugs that directly target pro-survival Bcl-2 proteins by mimicking the BH3 domain and unleashing pro-apoptotic molecules in tumor cells." (PMID 26447615, 2015). "Our results further demonstrate that CECs-Bcl-2, by binding to tumor cell, protect them in non-adherent conditions by providing a temporary substratum." (PMID 26509633, 2015). "This could serve as a mechanism for the sensitization since elevated levels of Bcl-2 and other proteins within the same family e.g. BCL-XL and MCL1 correlate with cisplatin resistance as well as tumor recurrence in NSCLC and other cancers." (PMID 26353782, 2015). "IHC revealed that the tumor diffusely expressed CD34, CD99, Bcl2, PAX8, NAB2, STAT6, and GRIA2." (PMID 26337721, 2015). "FISH analysis with the BCL2 break-apart probe disclosed breaks at 18q21 in all these cases and, additionally, in one tumor sample without obvious translocation in the karyotype." (PMID 24733537, 2014). "Interestingly, we found p-AKT and Bcl-2 downregulation in HCT-116 and MSTO-211 upon CF treatment, thus leading us to believe that CF can be used for the prevention of tumours and can possibly sensitize cancer cells to standard therapy." (PMID 24598211, 2014). "Immunohistochemically, the tumor cells were positive for S-100 protein, vimentin and BCL-2, and negative for HMB45, Melan-A, CD117, CD34 and CD99." (PMID 25364450, 2014). "Several molecular mechanisms are involved in the resistance to anoikis of tumor cells, including survival signaling driven by PI3K and NF-κB pathways, the expression of anti-apoptotic proteins such as Bcl-2, and the hyperactivation of tyrosine kinase receptors such as EGFR and ErbB2." (PMID 25788857, 2014). "The miR-34a downregulates numerous important regulatory proteins of cell cycle progression and apoptosis, such as E2F3, c-MYC, Bcl2, c-MET, and CDK4/6, suggesting that miR-34a itself may mediate tumor suppression." (PMID 24528540, 2014). "Alteration of the miR-15a and miR-16-1 translates into multiple tumor-promoting processes through the derepression of key cell cycle-and apoptosis-related genes such as B-cell CLL/lymphoma 2 (BCL2), wingless-type MMTV integration site family-member 3A (WNT3A) and cyclin D1 (CCND1)." (PMID 25309903, 2014). "In BLBC, other GATA3-controlled cellular pathways, or lack of downstream ER signaling, may compensate for upregulation of BCL2, THSD4 and DACH1 by GATA3, resulting in a tumor suppressor function." (PMID 25410484, 2014). "Previous studies have reported that mitochondrial autophagy induced by hypoxia requires the HIF-1-dependent expression of BNIP3, which plays a protective role by disrupting the Bcl-2-Beclin1 complex without inducing cell death in tumor cells." (PMID 25383959, 2014). "Bcl-2 is the first proto-oncogene that was found to aggregate tumor growth by decreasing the rate of apoptosis rather than by accelerating cell division." (PMID 24711740, 2014).